U8 (U8 small nucleolar RNA )
Gene: Small nucleolar RNA gene on chromosome 10 (5,004,710 to 5,004,842, forward strand). Ensembl gene ENSG00000239148.
Homologues: Orthologues: rabbit U8 (74% identical), mouse Gm24208 (62% identical), dog U8 (59% identical), mouse Gm25369 (54% identical), guinea pig U8 (53% identical). Paralogues in human: U8 (98% identical), U8 (80% identical), U8 (73% identical), U8 (70% identical), U8 (69% identical), U8 (68% identical), U8 (67% identical), U8 (66% identical), U8 (65% identical), U8 (62% identical), U8 (57% identical), U8 (54% identical), and 1 more.